HNRNPA2B1 (heterogeneous nuclear ribonucleoprotein A2/B1)
Diseases named in the same sentence as HNRNPA2B1 in open-access papers (continued):
Sharing a sentence is not in itself a finding about the gene and the disease.
tumor (continued). "Additionally, HNRNPA2B1, GOLGA8B and MAPK8IP3 were identified to be tightly associated with tumour progression and prognosis." (PMID 32485038, 2020). "Therefore, our results unraveled a feedback loop between hnRNPA2B1 and VHLα, which exerted tumor suppressor roles downstream aberrant c-myc signaling." (PMID 32826868, 2020). "HNRNPA2B1 also highly expressed in CRPC and associated with tumor progression and prognosis." (PMID 33343639, 2020). "Taken together, these results indicated that the levels of m6A modification and its regulator HNRNPA2B1 are increased in ESCC, and HNRNPA2B1 may play a critical role in tumor growth and metastasis of ESCC." (PMID 33134163, 2020). "Furthermore, we found that HNRNPA2B1 expression positively correlated with tumor diameter and lymphatic metastasis of ESCC." (PMID 33134163, 2020). "Roles of HNRNPA2B1 in promoting cell proliferation have been reported in human embryonic stem cells and diverse human cancer cell lines, such as regulating alternative splicing of tumor suppressors and oncogenes." (PMID 33273988, 2020). "The overexpression of RBM15B, METTL14, and HNRNPA2B1 is significantly related to tumor metastasis." (PMID 32582536, 2020). "What’s more, vivo study showed that the cells with higher expression of HNRNPA2B1 could induce bigger xenografted tumor in mice." (PMID 28077929, 2017). "Also, we found the tumor inhibitory rate of the PANC-1-KH group is the highest by using the PANC-1-OH group as a reference substance due to its highest expression of HNRNPA2B1." (PMID 28077929, 2017). "Indeed, elevated HNRNPA2B1 levels in tumours accelerate pre-mRNA processing via RNA binding, indicating the critical role of HNRNPA2B1 in the development of carcinoma." (PMID 28077929, 2017). "Moreover, lncCyt b, as well as its protein partner hnRNPA2B, should have physiological significance because all the tumor lines that we tested exhibited a decreased level of malignant properties, such as proliferation, migration and invasion, upon lncCyt b or hnRNPA2B1 was knocked down." (PMID 39869642, 2025). "Tumor-specific CRISPR knockouts or point mutants of YBX1, HNRNPA2B1, or ALIX (e.g., SUMO-site variants) could test their roles in exosomal miR-21, miR-200, miR-210 and PD-L1 loading, and the resulting effects on migration, T cell cytotoxicity, and TAM polarization." (PMID 41462674, 2025). "Considering H. pylori inducing hnRNPA2B1 expression in GC, we investigated whether H. pylori infection could mediate hnRNPA2B1 to modulate tumor metabolism by assessing the alterations in glucose uptake, the production of pyruvate and lactate, and NADP+/NADPH ratios." (PMID 38887155, 2024). "Furthermore, we delved into the interplay between HNRNPA2B1 expression and tumor immunity, as well as its relevance to immunotherapy, including immune cell infiltration, immune-related genes, immune checkpoints, chemokines and their receptors, immunotherapeutic response, and novel immunotherapies." (PMID 39268079, 2024). "Interestingly, PCK1 knockout partially counteracted tumor inhibition by hnRNPA2B1 knockout in mice." (PMID 38017546, 2023). "However, the association between abnormal HNRNPA2B1 levels and tumor prognosis and immunity in pan-cancer has not been reported." (PMID 35529270, 2022). "Together, HNRNPA2B1 might play an important role in tumor progression." (PMID 34277606, 2021). "Based on these findings, HNRNPA2B1 might play an important role in EMT during tumour development." (PMID 28077929, 2017). "Overall, this present research constructs a signature based on m6A reader enzyme HNRNPA2B1 on NSCLC antitumor response and ferroptosis for adjuvanting anti-tumor immunotherapy." (PMID 41271615, 2025). "The expression of HNRNPA2B1 correlates significantly with TMB, MSI, tumor stemness, and chemotherapeutic response, and it is implicated in the modulation of novel immunotherapies and the infiltration of a diverse array of immune cells." (PMID 39268079, 2024).
tumor (continued). "The m6A reader HNRNPA2B1 upregulates the expression of ACLY and ACC1, leading to the tumor progression of esophageal squamous cell carcinoma." (PMID 39457524, 2024). "The hnRNPA2B1 was validated to interact with DKK1 mRNA and repressed its expression, which led to activation of the Wnt/β-catenin pathway and tumor growth." (PMID 38481876, 2024). "Kaplan–Meier analysis and univariate Cox regression were conducted to assess the correlation between HNRNPA2B1 expression and DFI or PFI in tumor patients." (PMID 39268079, 2024). "IGF2BP1, HNRNPA2B1, FTO, WTAP promote the EC progression, but METTL3, METTL14, YTHDF2 work as tumor suppressors in EC." (PMID 39582531, 2024). "As for the mechanisms of these functions, we found that HNRNPA2B1 downregulated FRMD6, a tumor suppressor, by accelerating the maturation of miR-93-5p in an m6A-dependent manner." (PMID 37215455, 2023). "In contrast to the cancer research findings, knockout of HNRNPA2B1 by CRISPR/CAS9 method promotes the TNBC cell migration and invasion but alleviates tumor growth by activating the ERK-MAPK/Twist and GR-beta/TCF4 signaling pathways." (PMID 35462896, 2022). "HNRNPA2B1 regulates Wnt signaling transcriptional activity by regulating the stability of TCF7L2 mRNA, and it is related to tumor growth." (PMID 36157216, 2022). "Regarding tumor stemness, in this study, YTHDF2, HNRNPA2B1, HNRNPC, IGF2BP1, and KIAA1429 were positively correlated with tumor stemness, while FTO was negatively correlated with tumor stemness." (PMID 35003079, 2021). "Through the immunohistochemistry results of patient tumor tissues of 38 OSCC patients, we found that the protein levels of HNRNPA2B1 and LINE-1 are significantly positively correlated." (PMID 34631545, 2021). "The results showed that ELAVL1, YTHDF2, RBM15, HNRNPA2B1, ALKBH5A, and RBM15B expression was significantly upregulated in tumor tissues compared with normal tissues (p < 0.05)." (PMID 34900988, 2021). "The expression of m6A regulators with CNV amplification was significantly increased in CC samples compared to normal control samples, such as HNRNPA2B1, IGF2BP1, KIAA1429, and YTHDF1, while METTL14 and YTHDC2 were markedly decreased in the tumor specimens." (PMID 33500720, 2021). "On the contrary, METTL3, KIAA1429, RBM15B, HNRNPA2B1, and HNRNPC had significantly higher expression in tumor tissues (p < 0.001)." (PMID 34277622, 2021). "It appeared that IGF2BP1/3, ELAVL1, HNRNPA2B1, HNRNPC, KIAA1429, RBM15, LRPPRC, FMR1, YTHDF1/2 are highly expressed in the tumor while FTO, METTL14/16, WTAP, YTHDC1 and ZC3H13 are down-regulated." (PMID 35095993, 2021). "We observed DHX9 and MATR3 (in Tumor A, set 1), HNRNPC and LARP1 (in Tumor A, set 2), SRSF1 (in Tumor B, set 1 & Tumor B, set 2), SRSF6 and IGF2BP2 (Tumor B, set 2), HNRNPU (in Tumor B, set 2 & Tumor C, set 2), and FAM120A and HNRNPA2B1 (in Tumor C, set 2)." (PMID 31892958, 2020). "For example, MES GBMs (red arrows) were enriched for CAV1, CD44, CD63, RAB27A, SDCBP and SMPDL3A, while PN (blue arrows) tumours contained higher levels of transcripts for ANXA6, CD81, hnRNPA2B1, YBX1 (RNA binding proteins) and RAB35." (PMID 30034643, 2018). "It is also very imperative to mention here about our present observation, on the correlation of tumor potency of HepG2 cells by overexpressing HABP1 with the upregulation of oncogenic splicing factors SRSF1 and hnRNPA2B1." (PMID 29535843, 2018). "YBX1 has been identified as a key RNA-binding protein that selectively sorts miRNAs into exosomes, while HNRNPA2B1 directly regulates RNA cargo loading through post-translational modifications and has been validated by CRISPR knockout approaches in tumor models." (PMID 41462674, 2025). "One study demonstrated that delivering DNA-damaging drugs to the cell nucleus could activate hnRNPA2B1, which, through a downstream cGAS-dependent pathway, promotes the production of IFN-β, mediating an anti-tumor effect." (PMID 38523155, 2024).
tumor (continued). "Furthermore, HNRNPA2B1 exhibited higher expression in the tumor group of T cells, while HNRNPC showed increased expression in the tumor group of B cells, serving as a key mediator of PD-L1 expression in ESCC." (PMID 39199429, 2024). "In addition, the m6A readers, including YTHDF1/2/3, HNRNPC, HNRNPA2B1, RBMX, PRRC2A, and CPSF6, also demonstrated a higher expression in the tumor samples compared to the normal tissues." (PMID 38610981, 2024). "Importantly, by GO analysis, we found that the mRNAs in “hnRNPA2B1‐only” group (deleting the m6A modified genes from hnRNPA2B1‐RIP–seq) were enriched in cancer‐related pathways, such as tumor metabolism and translation processes." (PMID 38887155, 2024). "In addition, DCA was significantly positively correlated with Lrmp (a tumor promotion gene), and TDCA was significantly positively correlated with Hnrnpa2b1." (PMID 38982226, 2024). "YTHDC1, HNRNPC, HNRNPA2B1, YTHDF1, YTHDF2, and YTHDF3 all showed significantly high expression in ccRCC (all p-values < 0.0001) compared to the average overall gene expression in the tumour tissue." (PMID 36899967, 2023). "We also found the dependence of STARD14 on RNA methylation levels in LUAD, including the correlation with HNRNPA2B1, IGF2BP2, RBM15 and RBM15, which could participate in the tumor progression of LUAD." (PMID 37790851, 2023). "These outcomes suggest that the tumor suppressor effect of ANXA10 is related to m6A; ANXA10 may regulate HNRNPA2B1, IGF2BP3, METTL3, RBM15, YTHDF1 and YTHDF2 to affect the methylation level of LIHC." (PMID 36709331, 2023). "The IHC results indicated that about 67% of the tumor tissues (2 of 3) with low NUF2 expression showed negative or weak HNRNPA2B1 staining and 80% (8 of 10) of those with high NUF2 expression displayed moderate or strong HNRNPA2B1 staining." (PMID 36670423, 2023). "The HNRNPA2B1 phosphorylation levels between primary tumor tissues and normal tissue samples were examined using the CPTAC database." (PMID 35529270, 2022). "In addition, YTHDC1, YTHDF1, YTHDF2, IGF2BP3, HNRNPA2B1 and NKAP were confirmed by two databases to be positively correlated with tumor stage, which deserved more attention in the treatment of HCC." (PMID 35963644, 2022). "Moreover, we knocked down hnRNPA2B1 in U87MG and P3 and measured pri-miR-1298-5p in tumor cells and exosomes." (PMID 35501306, 2022). "MO-460 is a moracin-derived product that generates and accumulates SGs under hypoxic circumstances by binding and inhibiting hnRNPA2B1 and reducing HIF-1α protein production.hnRNPA2B1 has been identified as a unique molecular target in hypoxia-induced tumor survival." (PMID 35004322, 2021). "We found that the copy number loss of ZC3H13, FTO, YTHDC2, WTAP and ALKBH5 decreased the protein expression in tumor samples, and meanwhile, patients with amplification of IGF2BP3, HNRNPA2B1 and IGF2BP2 presented higher expression level of these three proteins than normal tissues." (PMID 32710725, 2020). "The data provided here suggest that hnRNPA2B1 serves as a crucial molecular target in hypoxia-induced tumor survival and thus offer an avenue for the development of novel anticancer therapies." (PMID 30755586, 2019). "Targeting hnRNPA2B1 using lentivirus‐mediated shRNA or blunting m6A mRNA export using the specific inhibitor STM2457 resulted in a remarkable reduction in BCSCs stemness and tumor initiation both in vitro and in vivo, thereby enhancing the therapeutic effect of doxorubicin." (PMID 38626369, 2024). "Moreover, the tissue microarray of 48 pairs of HCC tissues from patients showed that the expression of hnRNPA2B1 was more strongly expressed in tumor tissues of HCC higher than that in adjacent non-tumor tissues." (PMID 38017546, 2023). "To examine whether the MIR100HG/hnRNPA2B1/TCF7L2 axis plays a role in cetuximab resistance of CRC patients, we obtained paired tumor specimens from 12 individuals before the start of cetuximab treatment and at the time of tumor progression." (PMID 35279145, 2022).
tumor (continued). "All these findings imply that hnRNPA2B1 could be a novel tumor target and a biomarker for monitoring treatment response and evaluating prognosis; however, to the best of our knowledge, no imaging agents based on hnRNPA2B1 antibody have been reported to date." (PMID 36015303, 2022). "Besides, we validated the correlation of the other 6 DEMGs with immune cells, and found only HNRNPA2B1 had a positive correlation with almost every 6 immune infiltration cells in LUAD and LUSC, which may suggest a better anti-tumor immunity." (PMID 36261786, 2022). "Therefore, the expression levels of 7 m6A regulators (METTL14, YTHDC2, FTO, ALKBH5, HNRNPA2B1, VIRMA, and RBMX) were lower in both the OC tissues and the high-stage group, indicating their potential function as tumor suppressors in OC tumorigenesis and development." (PMID 34631700, 2021). "The HNRNPA2B1 was not overexpressed in tumor tissues in Segara Pancreas." (PMID 31355266, 2019). "After analyzing the relationship between HNRNPA2B1 and each clinical parameter from the TCGA database, we found that HNRNPA2B1 was overexpressed in tumors and HNRNPA2B1 expression was significantly correlated with tumor stage, T-class, and metastasis but without grade." (PMID 34631545, 2021). "Tumor tissue staining of YTHDF1 and HNRNPA2B1 showed moderate staining in the nucleus, and negative staining was observed in the normal tissues." (PMID 35372339, 2022). "Differential expression analysis indicated that the protein expression levels of KIAA1429, RBM15, HNRNPC, HNRNPA2B1, YTHDF1, YTHDF2, and YTHDC1 were higher in tumor samples than in non-tumor samples." (PMID 32582536, 2020). "Moreover, the MPs without drug promote tumor metastasis by promoting M2 macrophage differentiation, while the MTX-MP promotes M2 polarized toward M1 by activating lysosomal cytochrome P450 and nuclear hnRNPA2B1, thereby recruiting neutrophils to kill tumor cells." (PMID 39925807, 2025).
cancer (150 papers, 2008 to 2026). A tumor composed of atypical neoplastic, often pleomorphic cells that invade other tissues. "Overexpression of hnRNPA2B1 is found in many cancers and is closely associated with several malignant characteristics, including angiogenesis, metastasis, and treatment resistance." (PMID 39810713, 2025). "By analyzing the relationship between HNRNPA1B1 and genes involved in m1A, m5C, and m6A modifications, we confirmed that HNRNPA2B1 is associated with genes related to mRNA modifications across various cancers." (PMID 39268079, 2024). "We integrated TMB and HNRNPA2B1 gene expression data from pan-cancer samples and observed a significant association between HNRNPA2B1 and TMB in multiple tumors." (PMID 39268079, 2024). "We divided the cancer samples into high- and low-expression groups according to the expression value of HNRNPA2B1 and further analyzed the differences in somatic mutation distribution between the two groups." (PMID 39268079, 2024). "The results indicate that HNRNPA2B1 expression is significantly associated with these scores in the majority of cancers." (PMID 39268079, 2024). "Heterogeneous nuclear ribonucleoprotein A2/B1 (hnRNPA2B1) regulates the package of circEHD2 into EVs, then EVs-circEHD2 transmits to fibroblasts, converting fibroblasts to cancer-associated fibroblasts (CAFs)." (PMID 37481520, 2023). "Previous studies have reported that hnRNPA2B1 was inextricably associated with the MAPK signaling pathway in cancer development." (PMID 37716979, 2023). "We also included four additional splicing regulatory genes (HNRNPA2B1, HNRNPH1, HNRNPCL1, and SRPK1) because they are either related to cancer in general or have been associated with telomere biology (HNRNPA2B1:; HNRNPH1:; HNRNPCL1:; SRPK1:)." (PMID 37531400, 2023). "The current findings further suggested an association between HNRNPA2B1 and the infiltration of cancer-linked fibroblasts or Treg cells in different cancer types." (PMID 35529270, 2022). "It showed a positive relationship between HNRNPA2B1 and cancer-linked fibroblast infiltration in ACC and LUAD, but a negative relationship in STAD." (PMID 35529270, 2022). "The expression of hnRNPA2B1 has been implicated in various cancers, and its clinical use as a potential biomarker for cancer has been discussed." (PMID 36220838, 2022). "Recently, a few studies have described the association between HNRNPA2B1 and diseases, especially cancer." (PMID 35529270, 2022). "Many types of cancer exhibit HNRNPA2B1 overexpression, which is notably associated with poor prognosis." (PMID 35529270, 2022). "HNRNPA2B1 levels in LUAD were found to be positively associated with cancer-linked fibroblast infiltration (Rho = 0.238, P = 8.52e − 08)." (PMID 35529270, 2022). "Then, the KEGG enrichment investigation indicated that HNRNPA2B1 participates in the pathways associated with spliceosome, mRNA surveillance, and RNA degradation in cancers." (PMID 35529270, 2022). "Among them, the range of HNRNPA2B1 copy numbers is wide among various cancer types, and this is associated with the poor survival rate of LUAD." (PMID 36061307, 2022). "Overall, this pan-cancer analysis of HNRNPA2B1 revealed that HNRNPA2B1 overexpression is associated with changes in immune cell infiltration, spliceosome, and cell cycle signaling, as well as patient prognosis in various tumors." (PMID 35529270, 2022). "According to some bioinformatics analyses, HNRNPA2B1 is associated with other m6A regulators in various cancers." (PMID 35529270, 2022). "Similarly, ISGylation of heterogeneous nuclear ribonucleoprotein A2/B1 (hnRNPA2B1) mediated by prostate cancer associated transcript 6 (PCAT6) protects hnRNPA2B1 from ubiquitin-dependent degradation." (PMID 40103488, 2025). "Analysis of the effect of HNRNPA2B1 expression on immune cells and immune signatures in pan-cancer revealed that HNRNPA2B1 was closely associated with immune cell infiltration and immune signatures in the majority of cancers." (PMID 39268079, 2024).